IGKV2D-36 (immunoglobulin kappa variable 2D-36 (pseudogene))
Synonyms: IGKV2D36; O5
Gene: Immunoglobulin variable (V) pseudogene on chromosome 2 (89,887,022 to 89,887,247, forward strand). Ensembl gene ENSG00000253127.
Diseases named in the same sentence as IGKV2D-36 in open-access papers:
IGKV2D-36 is named in the same sentence as 2 diseases in open-access papers, as found by Europe PMC text mining. Sharing a sentence is not in itself a finding about the gene and the disease.
IGKV2D-36 shares sentences with these, for which no sentence is quoted: breast carcinoma (1 paper); infection (1).